KDM5C (lysine demethylase 5C)
Description:
Histone demethylase that specifically demethylates 'Lys-4' of histone H3, thereby playing a central role in histone code. Does not demethylate histone H3 'Lys-9', H3 'Lys-27', H3 'Lys-36', H3 'Lys-79' or H4 'Lys-20'. Demethylates trimethylated and dimethylated but not monomethylated H3 'Lys-4'. Participates in transcriptional repression of neuronal genes by recruiting histone deacetylases and REST at neuron-restrictive silencer elements. Represses the CLOCK-BMAL1 heterodimer-mediated transcriptional activation of the core clock component PER2 (By similarity).
Synonyms: DXS1272E; JARID1C; SMCX; XE169; MRX13; MRXJ; MRXS16; MRXSCJ; MRXSJ
Tractability: Small molecule: a structure with a bound ligand is known; a high-quality ligand is known; it belongs to a druggable protein family. PROTAC: UniProt records ubiquitination sites on it; ubiquitination databases record sites on it; its protein half-life has been measured; a small molecule that binds it is known.
Target class: Epigenetic regulator; Jumonji domain-containing; Eraser; Lysine demethylase
Gene: Protein-coding gene on chromosome X (53,176,277 to 53,225,422, reverse strand). Ensembl gene ENSG00000126012.
Subcellular location: Nucleus
Subcellular location (Human Protein Atlas): Nucleoplasm; Cytosol
Pathways (Reactome):
Chromatin organization: HDMs demethylate histones
Gene Ontology:
Molecular function: histone H3K4 demethylase activity; histone H3K4me/H3K4me2/H3K4me3 demethylase activity; protein binding; zinc ion binding; histone demethylase activity; DNA binding
Biological process: negative regulation of DNA-templated transcription; regulation of DNA-templated transcription; chromatin remodeling
Cellular component: nucleoplasm; nucleus; chromatin
Gene-disease validity (ClinGen):
ClinGen rates the evidence that KDM5C causes each of these diseases.
X-linked syndromic intellectual disability (X-linked): Definitive. A syndromic intellectual disability with an X-linked mode of inheritance.
Cancer hallmarks: proliferative signalling (promotes); suppression of growth (promotes); invasion and metastasis (promotes); genome instability and mutations (suppresses); escaping programmed cell death (promotes); escaping immune response to cancer (promotes); invasion and metastasis (suppresses)
Homologues: Orthologues: chimpanzee KDM5C (99% identical), macaque KDM5C (99% identical), rabbit KDM5C (98% identical), guinea pig KDM5C (78% identical), Drosophila melanogaster Kdm5 (42% identical), Caenorhabditis elegans rbr-2 (26% identical), zebrafish kdm4c (13% identical). Paralogues in human: KDM5D (85% identical), KDM5A (53% identical), KDM5B (46% identical), JARID2 (13% identical), KDM4B (13% identical), KDM4A (13% identical), KDM4C (12% identical), KDM4D (9% identical), KDM4F (8% identical), KDM4E (8% identical).
Diseases named in the same sentence as KDM5C in open-access papers:
KDM5C is named in the same sentence as 112 diseases in open-access papers, as found by Europe PMC text mining. Sharing a sentence is not in itself a finding about the gene and the disease. The quoted sentences say what the papers report.
Intellectual disability (36 papers, 2010 to 2026). "Mutations in KDM5C disrupt the homeostasis of the Wnt signaling pathway, leading to intellectual disabilities." (PMID 40761314, 2025). "We identified a gene from a Chinese family and found that a nonsense mutation of KDM5C was co-segregated with the intellectual disability (ID)." (PMID 39948613, 2025). "In conclusion, our study identified nonsense mutation of KDM5C was co-segregated with the intellectual disability (ID)." (PMID 39948613, 2025). "Our work identifies KDM5C as a crucial sentinel for neurodevelopment and sheds new light on KDM5C mutation-associated intellectual disability." (PMID 38383780, 2024). "The likely pathogenic variant in the KDM5C gene was consistent with Intellectual disability, X-linked, syndromic, Claes Jensen type, which is an X-linked recessive disorder." (PMID 39678379, 2024). "The demethylase KDM5C, mutations in which often lead to intellectual disability, is identified as a crucial player in regulating the precise timing of neurodevelopment together with the WNT signalling pathway." (PMID 38383780, 2024). "Defects in KDM5C activity result in X-linked intellectual disability in males and can result in mild intellectual disabilities in female carriers." (PMID 36945656, 2023). "Genes exhibiting such a behaviour included the zinc-finger protein ZFX and the histone demethylase KDM5C which is linked to intellectual disability and autism." (PMID 36802379, 2023). "In contrast to the gain of function seen in cancer cells, loss of function variants in the autosomal paralogs KDM5A, KDM5B, and the X-linked KDM5C have been observed in individuals with intellectual disability." (PMID 36803422, 2023). "We hereby describe a twenty-seven-year-old female patient diagnosed with moderate intellectual disability comorbid with other neuropsychiatric and behavioral issues carrying a de novo heterozygous stop variant in the KDM5C gene (NM_004187.5: c." (PMID 36553533, 2022). "For example, in mice, the X-linked gene kdm5c plays a crucial role in brain development and in humans, KDM5C mutations can result in neurodevelopmental abnormalities such as autism, intellectual disability and excessive aggression in males." (PMID 29662502, 2018). "Males with hemizygous mutations in KDM5C present with intellectual disability and facial dysmorphism, while most heterozygous female carriers are asymptomatic." (PMID 29456765, 2018). "Claes-Jensen syndrome is an X-linked inherited intellectual disability caused by mutations in the KDM5C gene." (PMID 29456765, 2018). "Mutations in the Kdm5c gene has been shown to be an important cause of intellectual disability selectively in males." (PMID 29662502, 2018). "Thirteen missense mutations associated with XLMR, the syndromic Claes-Jensen-type disease in KDM5C have been reported to date and affected individuals with KDM5C mutations show a mild-to-severe range of intellectual disability." (PMID 26580603, 2015). "Similarly, mutations in KDM5C (also known as JARID1C) have been linked to intellectual disability, X-linked, syndromic, Claes-Jensen type (MRXSCJ; OMIM 300534), and epilepsy." (PMID 40469903, 2025). "Claes-Jensen syndrome is an X-linked disorder caused by variants in KDM5C (JARID1C) which can affect both males and females with intellectual disability, seizures, short stature and craniofacial features; due to X-inactivation, only half of female carriers are affected." (PMID 36672956, 2023). "KDM5C encodes a histone demethylase involved in regulation of gene expression and DNA methylation, and LoF mutations in this gene have been shown to cause intellectual disability in females." (PMID 36117209, 2023). "Similarly, deficiency of lysine-specific demethylase 5C (KDM5C) alters the epigenetic state, which is associated with intellectual disability and frequent autistic behavior." (PMID 32244359, 2020).
Intellectual disability (continued). "Similar to the previous observations, all of these patients received low scores for the disease and carrier categories in our classification model, further suggesting that the epi-signature of KDM5C mutation is highly specific to Claes-Jensen type of intellectual disability." (PMID 29456765, 2018). "KDM5C-deficiency is characterized by frequent autistic and aggressive behaviors and is currently referred to as Mental Retardation, X-linked, Syndromic, Claes-Jensen type (MRXSCJ: OMIM#300534)." (PMID 29670509, 2018). "Using a genome-wide approach, we identified genes with significant loss of DNA methylation in blood of males with intellectual disability and mutations in the X-linked KDM5C gene, encoding a histone H3 lysine 4 demethylase, in comparison to age/sex matched controls." (PMID 23356856, 2013). "Finally our results shed light on the function of KDM5C as a transcriptional repressor and open up new avenues of research for elucidating the causes of mental retardation in patients with KDM5C deficiency." (PMID 20181063, 2010). "Loss-of-function mutations in the histone demethylases KDM5A, KDM5B or KDM5C are found in patients with intellectual disability and ASD." (PMID 41648108, 2026). "KDM5C is identified as a safeguard to ensure that neurodevelopment occurs at an appropriate timescale, the disruption of which leads to intellectual disability." (PMID 38383780, 2024). "Whole-exome sequencing of individuals with intellectual disability has identified loss of function mutations in KDM5A, KDM5B and KDM5C." (PMID 31862793, 2019). "Other members of the KDM family were also been identified as the disease genes for syndromic mental retardation, including KDM5C (MIM:314690) and KDM6A (MIM: 300128)." (PMID 27257017, 2016). "Another KDM5 family protein, JARID1C (also known as KDM5C and SMCX), has mostly been studied in context of mental retardation but has been linked to some forms of cancer." (PMID 21544224, 2011). "Changes to protein interactions could also contribute to the intellectual disability seen in individuals with genetic variants in KDM5A, KDM5B, or KDM5C." (PMID 36803422, 2023). "Moreover, two genes in the KDM5 family, KDM5B and KDM5C, are disrupted in neurodevelopmental disorders, including intellectual disability and ASD." (PMID 33350388, 2020). "In contrast to intellectual disability, which is exclusively associated with loss-of-function mutations in KDM5 genes, malignancies have been associated with overexpression of KDM5A or KDM5B, either loss or gain of KDM5C, or loss of KDM5D." (PMID 31862793, 2019). "For example, although some intellectual disability-associated mutations in KDM5C reduce in vitro histone demethylase activity, others do not." (PMID 31862793, 2019). "An in vitro study of variants in the histone demethylase KDM5C (Lysine demethylase 5C [MIM: 314690]), which is known to cause intellectual disability, showed that NTNG2 seemed to be important in mediating effects on neurite growth and length; these results are consistent with our findings here." (PMID 31668703, 2019). "In addition, mutations of KDM5C cause mental retardation, X-linked, syndromic, Claes-Jensen type [OMIM #300534] and mutations of IQSEC2 cause mental retardation, X-linked 1 [OMIM #309530]." (PMID 28414775, 2017). "We further show that this epi-signature is highly specific to KDM5C mutations, but not to the broad range of other Mendelian diseases resulting from the disruption of genes in the epigenomic machinery or other forms of developmental delay and intellectual disabilities (DD/ID)." (PMID 29456765, 2018). "However, the possible functions of KDM5C and CRBN in intellectual disability need to be further investigated." (PMID 39881283, 2025). "Duplications and deletions involving KDM5C, IQSEC2 and TSPYL2 that do not overlap with HUWE1, have also been shown to cause developmental delay, intellectual disability, behavioral disturbances and/or autistic features." (PMID 28414775, 2017).
breast cancer (25 papers, 2011 to 2026). A primary or metastatic malignant neoplasm involving the breast. "Kdm5c is found mutated in neurological disorders and in various cancer types, including clear cell renal cell carcinoma (ccRCC), breast cancer, and AML." (PMID 36631623, 2023). "Most of the patients with KDM5B gene mutation had a history of drinking, and most of the patients with KDM5C gene mutation had a family history of breast cancer, a history of chronic pancreatitis and a higher pancreatic cancer tumor grade." (PMID 35493099, 2022). "TRIM11 interacts with KDM5C, catalyzes K48-linked ubiquitin chain on KDM5C and regulates KDM5C stability in breast cancer cells." (PMID 36192394, 2022). "In breast cancer, the defect of lysine demethylase 5C (KDM5C) causes elevation of H3K4me3 on oncogene enhancers, which activates oncogene expression and tumorigenesis." (PMID 34409068, 2021). "In breast cancer, the defect of lysine demethylase 5C (KDM5C) causes H3K4 trimethylation and overactivation of oncogene enhancers, which then promotes oncogene expression and tumorigenesis." (PMID 33824309, 2021). "Collectively, these findings indicate that KDM5C degradation via TRIM11 promotes breast cancer cell proliferation and migration." (PMID 39394462, 2024). "This study further revealed that TRIM11 knockdown suppressed breast cancer cell proliferation and migration and that TRIM11 deficiency in animal models increased the KDM5C level and suppressed breast tumor growth." (PMID 39394462, 2024). "Our study demonstrates that TRIM11 promotes breast cancer through targeting KDM5C and reprogramming epigenetic modifications on enhancers." (PMID 36192394, 2022). "Our data show that TRIM11 and KDM5C regulate the expression of MCAM in breast cancer cells, through targeting an enhancer close to MCAM TSS." (PMID 36192394, 2022). "We divided the tissues into four subgroups according to the provided information of molecular marks, and found that TRIM11 was higher expressed and KDM5C was lower expressed in all four groups of breast cancer tissues." (PMID 36192394, 2022). "KDM5C is a switching factor that balances the regulation of ER signaling and tamoxifen-induced sensitization in breast cancer cells." (PMID 35453496, 2022). "We found that TRIM11 knockdown elevated KDM5C protein level in breast cancer cell lines MDA-MB-231, MDA-MB-468, and kidney cell lines HEK293T, but did not affect its mRNA level." (PMID 36192394, 2022). "All these indicated that TRIM11 plays an oncogenic role in breast cancer animal model and regulates KDM5C in breast cancer tissues." (PMID 36192394, 2022). "Overexpression of KDM5C increases breast cancer cell proliferation and tumorigenesis by modulating the H3K4 methylation status and consequently promotes endocrine therapy resistance." (PMID 35453496, 2022). "To further explore the relationship between TRIM11 and KDM5C in breast cancer patient tissues, we performed immunohistochemical (IHC) staining with commercially available breast cancer tissue arrays." (PMID 36192394, 2022). "Analysis of patient survival rate with TCGA breast cancer data show that patients with higher MCAM expression have worse survival rate, further supporting that regulation of MCAM by TRIM11 and KDM5C is important for breast cancer." (PMID 36192394, 2022). "KDM5C is considered as a tumor suppressor through regulating enhancer function in several types of cancer, such as breast cancer, clear cell renal carcinoma and cervix cancer." (PMID 36192394, 2022). "TRIM11 regulates proliferation and migration of breast cancer cells through KDM5C, and TRIM11 promotes breast cancer and regulates KDM5C stability in an in vivo animal model." (PMID 36192394, 2022). "To further investigate the molecular mechanisms for TRIM11 and KDM5C in regulating breast cancer, we performed RNA-Seq and ChIP-Seq analysis in TRIM11 or KDM5C knockdown cells derived from MDA-MB-231." (PMID 36192394, 2022).
breast cancer (continued). "The detailed mechanisms how KDM5C is involved in breast cancer should be further investigated in the future." (PMID 36192394, 2022). "Taken together, our data suggested that simultaneously blocking ERα signaling by ERα antagonist and KDM5C activity by KDM5C inhibitor is an effective way to suppress ERα‐positive breast cancer cell and tumor growth." (PMID 33977073, 2021). "As KDM5C's function in suppressing type I IFNs and ISGs in breast cancer is apparently dependent on its enzymatic activity, small molecule inhibitors targeting KDM5C enzymatic activity will certainly enhance tumor immunogenicity." (PMID 33977073, 2021). "Out of all the demethylases that were found to be required for estrogen‐induced ERα‐positive breast cancer cell growth, KDM5C was particularly interesting partially due to its clinical relevance." (PMID 33977073, 2021). "Taken together, our data suggested that KDM5C activates estrogen‐target genes to promote breast cancer cell growth and tumorigenesis." (PMID 33977073, 2021). "In the current study, through systematic screening of the histone demethylase family proteins, we identified KDM5C as one of the candidates which co‐activate estrogen/ERα‐driven gene transcription and promote the growth of ERα‐positive breast cancer cells." (PMID 33977073, 2021). "Pharmacological inhibition of both ERα signaling and KDM5C was shown to be effective in inhibiting ERα‐positive breast cancer cell growth and tumorigenesis." (PMID 33977073, 2021). "In contrast, KDM5C plays a tumor-suppressing role in cervical cancer, breast cancer and renal carcinoma." (PMID 32714863, 2020). "In contrary, KDM5C acts as a tumor suppressor in clear cell renal carcinoma (ccRCC), cervical cancer and breast cancers." (PMID 32714863, 2020). "KDM5C has been reported to repress transcription in post-mitotic neurons and breast cancer cells, whereas KDM5C can promote gene expression when it acts on specific transcriptional enhancers in mouse embryonic stem cells." (PMID 29670509, 2018). "KDM5C is believed to promote cell growth by activating estrogen receptor target genes and evade immune surveillance by inhibiting type I interferons and interferon-stimulated genes, thereby facilitating the proliferation of breast cancer cells." (PMID 40608007, 2025). "The mRNA level of KDM5C is significantly lower in some breast cancer datasets." (PMID 36192394, 2022). "These suggest that TRIM11 plays oncogenic roles in many types of cancer, while KDM5C may be behaves as a tumor suppressor only in breast cancer." (PMID 36192394, 2022). "In addition, KDM5C was found to promote cell growth in another two ERα‐positive breast cancer cell line, T47D and BT474." (PMID 33977073, 2021). "KDM5C's oncogenic role in ERα‐positive breast cancer prompted us to examine whether it is required for estrogen/ERα‐induced gene transcriptional activation." (PMID 33977073, 2021). "Furthermore, KDM5C's effects on representative estrogen‐target genes were demonstrated in another two ERα‐positive breast cancer cell line, T47D and BT474." (PMID 33977073, 2021). "Our data above suggested that KDM5C activates estrogen/ERα‐target gene independent on its enzymatic activity, while represses type I IFNs and ISGs in an enzymatic‐dependent manner, with both are beneficial for breast cancer cell growth and tumorigenesis." (PMID 33977073, 2021). "Ablation of either ZMYND8 or KDM5C in ZR-75-30 breast cancer cells results in over-activation of their target enhancers, characterized by the deposition of H3K4me3 and H3K27ac, decreased H3K4me1, and increased transcription of enhancer RNAs (eRNAs) and nearby genes." (PMID 33670804, 2021). "In order to make clear the way KDM5C regulates FASN expression, we analyzed the public ChIP-seq database which is processed by Cistrome analysis pipeline, and found a strong binding site of KDM5C in the promoter region of the gene locus of FASN in breast cancer cells." (PMID 32714863, 2020).